HIF1A (hypoxia inducible factor 1 subunit alpha)
Diseases named in the same sentence as HIF1A in open-access papers (continued):
Sharing a sentence is not in itself a finding about the gene and the disease.
cancer (continued). "It is well known that PTEN is a lipid phosphatase whose loss activates PI3K/AKT signaling, which is related to HIF1α upregulation and enhanced angiogenesis in some human cancer cells." (PMID 25896712, 2015). "This study explores the underlying mechanism by which TM mediates degradation of HIF-1α and identifies a therapeutic advantage for the use of TM in targeting chemo-resistant cancer cells." (PMID 26469226, 2015). "The dysregulation of HIF1α and Aurora-B are implicated in many aspects of cancer development and advancement." (PMID 25788277, 2015). "Blocking the expression of HIF1α should, in theory, block its induction of a cascade of proteins associated with cancer invasion, proliferation, and metastasis." (PMID 26501324, 2015). "This possibility will be better addressed in HIF-1α-deficient cancer cells or conditional genetic models." (PMID 25893706, 2015). "Loss of HIF-1α results in an increased angiogenic response in human cancer cells and increased mortality in Drosophila following infection." (PMID 25510503, 2015). "In the recent years, a good number of studies have investigated the impact of HIF1A polymorphisms on cancer risk in different populations; however reported results varied across studies and remain inconclusive." (PMID 26715988, 2015). "HIF-1α overexpression has been associated with increased patient mortality in many different human cancers." (PMID 25733977, 2015). "Loss of HIF-1α results in an increased angiogenic response in mammalian cancer cells and increased mortality in Drosophila following infection." (PMID 25510503, 2015). "Intratumoral hypoxia and genetic alterations lead to HIF-1α overexpression, which has been associated with increased patient mortality in several cancer types." (PMID 26228921, 2015). "It has been demonstrated that loss of LKB1 makes cancer cells rely on HIF-1α in the ATP supply, which induces an increase in glycolysis and glutamine consumption." (PMID 26402672, 2015). "It is also reported that mitochondrial defect linked stabilization of HIF1α induces glycolytic phenotype in cancer cells and promotes aggressiveness of tumors." (PMID 25925410, 2015). "microRNA-210 (miR-210), a hypoxia-responsive microRNA regulated by HIF-1α, has been implicated in cancer and cardiovascular disease formation." (PMID 26254226, 2015). "A few studies have focused on the association between the polymorphisms in HIF1A gene and cancer risk or prognosis." (PMID 26115041, 2015). "Meta-analysis from this study indicated that HIF1A 1772 C/T polymorphism is significantly associated with overall cancer risk." (PMID 26715988, 2015). "In the scientific community, HIF1A has been a research focus and a number of SNPs within HIF1A gene have been identified in association with cancers, with the most widely studied polymorphisms are C1772T (rs11549465) and G1790A (rs11549467) polymorphisms." (PMID 26715988, 2015). "In this study, the effect of rs11549465 (1772 C/T) and rs11549467 (1790 G/A) polymorphisms of HIF1A gene and its association with cancers were investigated through meta-analysis." (PMID 26715988, 2015). "In this study, the effect of rs11549465 (1772 C/T) and rs11549467 (1790 G/A) polymorphisms of HIF1A gene and its association with cancers were investigated systematically through meta-analysis." (PMID 26715988, 2015). "HIF-1α, a transcription factor, has been demonstrated to be associated with most hypoxic solid tumors and is consistently upregulated in various types of cancers and promotes tumorigenesis through angiogenesis." (PMID 25649293, 2015). "While HIF-1α has been associated with platinum resistance in a variety of cancers, including ovarian, relatively little is known about the importance of the duration of hypoxia." (PMID 26205780, 2015). "Since Akt phosphorylation is intimately linked to HIF-1α activation, it is likely nobiletin exerts its cancer fighting properties through blocking Akt phosphorylation." (PMID 25845666, 2015).
cancer (continued). "Activation of HIF1α by hypoxia is known to be associated with a glycolytic phenotype in many cancer cells, with a substantial increase in glucose uptake." (PMID 26087400, 2015). "The initial expectation that HIF-1α should be increased in TNBC comes from its high documented levels in hereditary BRCA1 mutated carcinomas (up to 90% of cases)." (PMID 26046764, 2015). "HIF-1α protein is over-expressed in multiple types of human cancer and is the major cause of resistance to drugs and radiation in solid tumours." (PMID 24804733, 2014). "In clinical studies focusing on the association between HIF1α expression and prognosis of cancers, the conclusions were contradictory." (PMID 24567056, 2014). "The hypoxia inducible factor-1α (HIF-1α) is one of the pivotal regulators of angiogenesis in response to oxygen deficiency and has been found overexpressed in many human cancers." (PMID 25093990, 2014). "The results indicated that the overall significance of the pooled ORs was not altered by any single study in the genetic models for the HIF-1α C1772T/G1790A polymorphisms and cancer susceptibility, suggesting stability and reliability in our overall results." (PMID 25496056, 2014). "In the present study, we tried to elucidate the effect of nutrient deprivation on HIF-1α accumulation in cancer cells and the underlying molecular mechanism." (PMID 25115400, 2014). "The aim of this study is to investigate the relationship of HIF-1α gene G1790A polymorphism with cancer using meta-analysis." (PMID 24808762, 2014). "Pooled odds ratios (ORs) and corresponding 95% confidence intervals (CIs) for the relationship between HIF-1α C1772T/G1790A polymorphisms and cancer susceptibility were calculated using fixed- and random-effects models when appropriate." (PMID 25496056, 2014). "In many cancer cells, abnormal expression of HIF-1α has been described and associated with induction of pro-survival signalling pathways (such as MAPK, PI3K cascades) and c-MYC oncogene, as well as the metabolic shift known as Warburg effect." (PMID 24732040, 2014). "Hypoxia-inducible factor 1α (HIF-1α) is a transcription regulation factor that is closely associated with the development of malignant tumors." (PMID 25013467, 2014). "In order to obtain a more comprehensive knowledge of the association between HIF-1α G1790A polymorphism and cancer risk, a meta-analysis on eligible case–control studies was conducted." (PMID 24808762, 2014). "Recently, a large number of epidemiological studies have investigated the relationship between HIF-1α C1772T/G1790A polymorphisms and cancer susceptibility." (PMID 25496056, 2014). "HIF-1α gene single nucleotide polymorphisms (SNPs) are implicated to be associated with cancer risks." (PMID 24808762, 2014). "HIF-1α protein is overexpressed in multiple types of human cancer and is associated with worse prognosis in many cancers." (PMID 24901645, 2014). "HIF-1α is known to play a major role in tumorigenesis, through activation of several genes implicated in many aspects of cancer progression and prognosis." (PMID 25420025, 2014). "Different types of mutations can affect HiF-1α regulation in cancer cells, leading to its pathological accumulation." (PMID 25338163, 2014). "This is consistent with findings by others indicating hypoxia independent upregulation of HIF-1α in cancer cells by loss of function of tumor suppressor genes and gain of function of oncogenes." (PMID 24472707, 2014). "Over the last few years, a great number of studies have been performed to investigate the association between these HIF-1α polymorphisms and cancer risk in different populations." (PMID 25496056, 2014). "The possible association between HIF-1α SNPs and cancer risk has been studied by several investigators, but the results were inconclusive or even contradictory." (PMID 24808762, 2014).
cancer (continued). "After sensitivity analyses were performed, our results did not vary substantially, which strongly suggests an association between the HIF-1α G1790A polymorphism and increased cancer risk." (PMID 25496056, 2014). "HIF-1α overexpression is commonly found in numerous types of human cancer and is often associated with tumor progression and poor prognosis." (PMID 24940418, 2014). "Clearly, as it is an over-simplified model, it cannot reflect the exact response of the HiF-1α regulation system to mutations and anti-cancer therapies." (PMID 25338163, 2014). "It will be necessary to perform additional research to evaluate the relationship between HIF-1α C1772T/G1790A polymorphisms and cancer risk." (PMID 25496056, 2014). "Alternatively, loss-of-function mutations in pVHL or the enzymes involved in the metabolism of PHD cofactors cause the accumulation of HIF-1α in cancers." (PMID 25420025, 2014). "Proteins encoded by HIF-1α target genes that are involved in key aspects of cancer biology, including cell proliferation and metabolism." (PMID 24505470, 2014). "In the current study, we summarized the latest data on the association between G1790A of HIF-1α gene polymorphism and cancer risk." (PMID 24808762, 2014). "It has the ability to influence metabolic reprogramming, angiogenesis, metastasis and recent studies found that HIF-1α was associated with many kinds of cancer." (PMID 24367595, 2013). "It is well established that HIF-1α can promote angiogenesis; however, tumour hypoxia is also linked to increased metastatic potential in several types of cancers." (PMID 23740575, 2013). "In the present meta-analysis, we investigated the association of HIF-1α 1772 C/T and 1790 G/A polymorphisms with cancer risk." (PMID 24260383, 2013). "The HIF-1α/VEGF/PEDF signaling is closely associated with cancer cell growth, migration and angiogenesis." (PMID 23869238, 2013). "Hypoxia is one of the most universal hallmarks of cancer and the transcription factor HIF-1α mediates a majority of cancer-associated transcriptional changes." (PMID 23530113, 2013). "Totally, no significant heterogeneity was observed among studies for the associations between HIF-1α C1772 T polymorphism and cancer metastasis in the pooled analysis and stratified analysis of dominant model." (PMID 24015181, 2013). "We conducted a comprehensive meta-analysis to estimate the associations between HIF-1α C1772 T polymorphism and cancer metastasis." (PMID 24015181, 2013). "The meta-analysis investigates the associations between HIF-1α C1772 T polymorphism and cancer metastasis." (PMID 24015181, 2013). "The possible association between HIF-1α C1772T polymorphism and cancer risk has been studied extensively." (PMID 24367595, 2013). "Accordingly, we performed a meta-analysis on eligible case–control studies to produce a more powerful estimation of the association of HIF-1α 1772 C/T and 1790 G/A polymorphisms with cancer risk." (PMID 24260383, 2013). "For HIF1A A588T polymorphism, the A allele was significantly correlated with higher urinary cancers risk in Asian population (OR = 1.41, 95% CI = 1.03–1.93, Pheterogeneity = 0.22, P = 0.03)." (PMID 23723982, 2013). "HIF-1α 1772 C/T and 1790 G/A genetic polymorphisms were previously suggested to be responsible for the risk for various types of cancer." (PMID 24260383, 2013). "A number of studies have showed the relationship between the HIF-1α C1772T polymorphism and cancer metastasis, but the results have been disparate." (PMID 24015181, 2013). "HIF-1α 1772 C/T and 1790 G/A polymorphisms are reportedly associated with cancer risk; however, the results are inconclusive." (PMID 24260383, 2013). "Increased cGMP-mediated ERK phosphorylation is associated with low levels of NO in cancer cells whereas HIF-1a stabilization is associated with intermediate levels." (PMID 23509693, 2013). "The meta-analysis for the HIF-1α 1790 G/A polymorphism included 4884 cancer cases and 8154 controls." (PMID 24260383, 2013).
cancer (continued). "The aim of this study was to investigate the association between HIF-1α C1772 T polymorphism and cancer metastasis." (PMID 24015181, 2013). "This meta-analysis shed light on the association between HIF-1α polymorphisms and increased risk for various cancers." (PMID 24260383, 2013). "A), the dominant mode (TT+CT vs. CC) showed that there were significant associations between HIF-1α C1772 T and cancer metastasis (OR = 1.39, 95% CI = 1.13–1.71, P = 0.002, Pheterogeneity = 0.27." (PMID 24015181, 2013). "To better explore the associations of HIF-1α C1772T polymorphism with cancer metastasis, we conducted a meta-analysis to collect and analyze the published data." (PMID 24015181, 2013). "A meta-analysis has proved that the HIF-1α C1772 T polymorphism is significantly associated with higher cancer risk." (PMID 24015181, 2013). "High activity of the PI3 kinase-AKT signaling pathway in cancer cells appears to be causally related to the increased expression of HIF-1α and c-myc." (PMID 23866118, 2013). "We used the OR and 95%CI to assess the associations between HIF-1α C1772T polymorphism and cancer metastasis." (PMID 24015181, 2013). "There was an evidence to indicate that the HIF-1α C1772T polymorphism was significantly associated with increased risk of cancer metastasis among Asians and Caucasians only for dominant genetic model." (PMID 24015181, 2013). "High HIF-1α levels have been associated with poor prognosis in most cancers, including epidermal carcinogenesis." (PMID 24367595, 2013). "The results showed that HIF-1a C1772T polymorphism was associated with the increased risk of cancer metastasis (T allele vs. C allele, OR = 1.36, 95% CI = 1.12–1.64; TT+ TC vs. CC, OR = 1.39, 95% CI = 1.13–1.71; TT vs. TC+ CC, OR = 1.93, 95% CI = 0.86–4.36)." (PMID 24015181, 2013). "Recently, HIF1A gene polymorphisms have been evaluated for a probable role in mediating genetic predisposition to cancer." (PMID 23723982, 2013). "The possible association between HIF-1α C1772T and cancer risk has been investigated in several studies, but the results were inconclusive or even contradictory." (PMID 24367595, 2013). "Main results of the meta-analysis for the association of HIF1A gene 1772 C/T and 1790 G/A polymorphisms with cancer risk." (PMID 24260383, 2013). "HIF1A (hypoxia-inducible factor 1α) is the master regulator of the cellular response tohypoxia and is implicated in cancer progression." (PMID 23398456, 2013). "The pooled OR for C vs. T and TT/CT vs. CC indicated that HIF-1a C1772T was significantly associated with a increased risk of cancer metastasis." (PMID 24015181, 2013). "Stimulation of glycolysis in cancer cells under hypoxic conditions is thought to be mediated largely by activation of the transcription factor HIF-1α, a master regulator of genes encoding a number of components of the glycolytic pathway." (PMID 23866118, 2013). "In summary, our meta-analysis reveal that the HIF-1α C1772T polymorphism can increase the risk of cancer metastasis." (PMID 24015181, 2013). "The overexpression of HIF-1α has been associated with the poor prognosis of various types of cancer." (PMID 24260057, 2013). "To date, numerous studies have addressed the molecular mechanisms underlying invasion/metastasis related to hypoxia/HIF-1α in human cancers." (PMID 24216696, 2013). "HIF-1α overexpression is observed in >70% of human cancers and is associated with poor patient prognosis and resistance to radio- and chemotherapy." (PMID 24403227, 2013). "More studies on gene–gene and gene–environment interactions should also be considered in the future to obtain a more comprehensive understanding of the association between HIF-1α polymorphisms and cancer risk." (PMID 24260383, 2013).
cancer (continued). "Altered HIF binding due to methylation changes in HREs has been further validated in additional target genes, such as BNIP3 or HIF1A, and is often associated with cancer progression." (PMID 23029193, 2012). "This was associated with increased expression of HIF-1α which controls inflammation, and activates the transcription of genes involved in crucial aspects of cancer biology, including angiogenesis." (PMID 22239913, 2012). "Generally, a loss of VHL expression in cancer leads to up-regulation of HIF-1α and increased VEGF expression." (PMID 22390300, 2012). "Significant associations between HIF-1α overexpression and patient mortality have been shown in many different cancers, including those of the brain, breast and cervix." (PMID 22211243, 2012). "HIF-1α expression is frequently increased in many human cancers and is associated with angiogenesis induced by tumors and hypoxia." (PMID 22442669, 2012). "Both clinical and experimental studies have revealed a significant association between the expression of HIF-1α and development and prognosis of malignant tumors." (PMID 23300882, 2012). "Until recently TIMP-1 and HIF-1α (and in consequence miR-210) were seemingly totally un-related factors whose elevation is associated with bad prognosis for cancer patients." (PMID 22807917, 2012). "HIF-1α overexpression has been associated with poor prognosis in patients with various types of cancer." (PMID 22211243, 2012). "Androgen receptor, c-Myc and HIF-1α activity are associated with poor prognosis in many cancers, including PCa." (PMID 22087262, 2011). "Mutant IDH1 expression can up-regulate hypoxia inducible factor 1α (HIF-1α), a transcription factor that has been implicated in promoting angiogenesis and malignant behavior of cancer cells." (PMID 21326614, 2011). "Hypoxia is a common characteristic of many aggressive tumors and there are several reports associating HIF-1α/2α expression with the patients' outcome in a broad range of cancers." (PMID 20624283, 2010). "Knockdown of HIF-1α by RNA interference (RNAi) remarkably sensitized cancer cells with oncogenic Ras mutations or those with PTEN inactivation or deletion to cetuximab treatment." (PMID 21209911, 2010). "In summary, our findings indicate that 1, 9 PA can sensitize cancer cells to cetuximab-mediated anti-EGFR therapy by downregulating HIF-1α and can enhance cellular response to cetuximab treatment in cancer cells bearing oncogenic Ras mutations." (PMID 21209911, 2010). "Using real-time quantitative reverse transcription PCR assays, we measured mRNA concentrations of total HIF-1α and 4 variants in breast tissue specimens in a series of 29 normal tissues or benign lesions (normal/benign) and 53 primary carcinomas." (PMID 20624301, 2010). "The meta-analysis for the HIF-1α 1772 C/T polymorphism included 4131 cancer cases and 5387 controls." (PMID 20035632, 2009). "The meta-analysis for the HIF-1α 1790 G/A polymorphism included 2058 cancer cases and 3026 controls." (PMID 20035632, 2009). "In this meta-analysis, we aimed to investigate the association between HIF-1α 1772 C/T and 1790 G/A polymorphisms and cancer." (PMID 20035632, 2009). "The molecular basis of gender specific effect of the HIF-1α 1772 C/T polymorphism on cancers is unclear." (PMID 20035632, 2009). "HIF-1α gene polymorphisms have been investigated for a possible role in mediating genetic predisposition to cancer." (PMID 20035632, 2009).